SNAI2 (snail family transcriptional repressor 2)
Diseases named in the same sentence as SNAI2 in open-access papers (continued):
Sharing a sentence is not in itself a finding about the gene and the disease.
head and neck squamous cell carcinoma (8 papers, 2018 to 2025). A squamous cell carcinoma that arises from any of the following anatomic sites: lip and oral cavity, nasal cavity, paranasal sinuses, pharynx, larynx, and salivary glands. "Similarly, TNF-α can inhibit Snai2 ubiquitination in head and neck squamous cell carcinoma by suppressing the NF-κB signaling pathway, promoting EMT and metastasis." (PMID 39062049, 2024). "In head and neck squamous cell carcinoma (HNSCC), by facilitating sphere formation, inducing stem-cell-related factor expression, and enhancing chemoresistance to cisplatin, SNAI2 enhanced the self-renewal capacity of cells." (PMID 36674577, 2023). "In addition, Snai2 plays a role in promoting cancer stem cell-like properties in tumor tissues such as head and neck squamous cell carcinoma (HNSCC) and pancreatic cancer." (PMID 40919166, 2025). "SNAI2 is an EMT-promoting TF that stimulates the expression of matrix metallopeptidase 9, thereby maintaining long-term EMT promotion in head and neck squamous cell carcinoma." (PMID 36567723, 2022). "Indeed, EZH2 did not regulate SNAI1 or SNAI2 gene expression in head and neck squamous cell carcinoma cell lines, and the inhibition of its expression repressed the expression of mesenchymal markers and inhibited migration and invasion capacities without modulating EMT-TF levels." (PMID 33291363, 2020).
leukemia (8 papers, 2018 to 2025). A malignant (clonal) hematologic disorder, involving hematopoietic stem cells and characterized by the presence of primitive or atypical myeloid or lymphoid cells in the bone marrow and the blood. "Taken together, these studies underscore SNAI2’s oncogenic role in leukemia biology, influencing stem cell dynamics and conferring drug resistance, each aspect offering potential opportunities for therapeutic intervention." (PMID 39200378, 2024). "It has been shown that SNAI2, like SNAI1, is closely linked with the progression and treatment response of leukemia." (PMID 39200378, 2024). "SNAI2 promotes leukemogenesis, and its loss or pharmacological inhibition impairs leukemic stem cell (LSC) self-renewal and delays leukemia progression." (PMID 39200378, 2024). "Similarly, SNAI2 differentially regulates the potential for self-renewal in leukemia stem cells (LSCs), and normal hematopoietic stem cells (HSCs)." (PMID 36674577, 2023). "Moreover, SNAI2 promoted leukemogenesis, but SNAI2 deficiency impaired LSC self-renewal and delayed leukemia progression." (PMID 36674577, 2023). "Furthermore, Snai2 knock out was able to reduce the ability of MLL-AF9 and NUP98-HoxA9 oncogenes to transform mouse HSCs in vivo, while limiting dilution assays demonstrated reduced LSC/LIC frequencies in Snai2 knockout MLL-AF9 leukemia." (PMID 37600794, 2023).
lymph node metastasis (8 papers, 2018 to 2024). "Although SNAI2 mRNA expression level is associated with lymph node metastasis in tongue SCC, this is the first time it was associated with lymph node metastasis in PeC." (PMID 35806108, 2022). "SNAI2 levels were higher in bone metastases than in liver and lymph node metastases (left) and were significantly associated with lethality and OS (right)." (PMID 34792282, 2022). "Upregulation of SNAI2 significantly correlates with strong vimentin expression, and both SNAI2 and vimentin expression is associated with lymph node metastasis and poor prognosis." (PMID 31641356, 2019).
oral squamous cell carcinoma (8 papers, 2013 to 2026). "Our result is also supported by another report that inhibiting ERK signaling blocked TGF-β1-induced SNAI2 expression in oral squamous cell carcinoma cells." (PMID 24260309, 2013). "For instance, in oral squamous cell carcinoma, FOXD1 promotes the epithelial–mesenchymal transition (EMT) by activation of SNAI2." (PMID 35954332, 2022). "Additionally, DRP1 knockdown-induced imbalanced mitochondrial dynamics in oral squamous cell carcinoma cells suppress stemness and drive ferroptosis by enhancing glutaminolysis via the ASCT2/SNAI2 axis." (PMID 41601687, 2026).
endometrial cancer (7 papers, 2010 to 2023). Primary or metastatic malignant neoplasm involving the endometrium (mucous membrane that lines the endometrial cavity). "For SNAI2, amplification was the most frequent alteration, with 4.43% on breast invasive carcinoma, and of 3.06% in endometrial carcinoma." (PMID 35898399, 2022). "SNAI1, SNAI2, TWIST, and ZEB EMT TFs have been reported to be involved in EMT in endometrial cancer cell lines." (PMID 36766756, 2023). "Recently, for endometrial cancer similar observations have been described confirming promoter-binding sites for the Wnt/β-catenin inducing transcription factor LEF-1 and, interestingly, also for the EMT inducing transcription factors SNAI1 and SNAI2." (PMID 22295114, 2012).
invasive breast carcinoma (7 papers, 2014 to 2024). A carcinoma that infiltrates the breast parenchyma. "In the invasive breast cancer subset, tumors with the highest expression of SNAI2 had a significantly poorer likelihood of progression-free survival, and high SNAI2-expressing tumors were enriched significantly in the claudin-low subtype." (PMID 39327614, 2024).
prostate tumor (7 papers, 2017 to 2025). "In addition, our results show that significant association of SNAI2 mRNA downregulation with metastatic prostate tumor tissues compared to normal and primary prostate tissues." (PMID 31060254, 2019). "SNAI2 (snail family transcriptional repressor 2) can regulate prostate tumor progress, angiogenesis, and metastasis potentially by modulating the GSK-3β/β-catenin signaling pathway." (PMID 35768705, 2022). "We show that EMT characterizes acutely resistant prostate tumors and that deletion of SNAI2, a key transcriptional regulator of EMT, correlates with clinical response." (PMID 34322653, 2021). "We confirmed that methylation of SNAI2 was significantly increased in primary prostate tumors compared to normal prostate tissue and showed negative correlation with SNAI2 mRNA in TCGA (r = −0.73, P = 3.21e‐85)." (PMID 34792282, 2022).
pulmonary fibrosis (7 papers, 2020 to 2025). Chronic progressive interstitial lung disorder characterized by the replacement of the lung tissue by connective tissue, leading to progressive dyspnea, respiratory failure, or right heart failure. "We next addressed how the expression of EMT-inducing transcription factors, Snai1, Snai2, Twist1, Twist2, Zeb1 and Zeb2, changed in the lungs from WT and Plaur-/- mice at Day 7, 14, 21 and 28 after bleomycin-induced pulmonary fibrosis." (PMID 36674896, 2023).
Waardenburg syndrome (7 papers, 2017 to 2024). "In the catalog (CD−M7), Pou3f4, Homer2, and Col11a2 were associated with NSHL, Snai2 with Waardenburg syndrome, Lars2 with Perrault syndrome, and Col11a2 with otospondylomegaepiphyseal dysplasia." (PMID 39684410, 2024). "Waardenburg syndrome is genetically heterogeneous and results from mutations in Sox10, Pax3, Mitf, Snai2, Ednrb, and Edn3, as well as many cases with unidentified mutations." (PMID 32912160, 2020). "SNAI2, a transcriptional repressor involved in melanocyte migration and associated with pigmentary disturbances in some types of Waardenburg syndrome, was down-regulated in all three cell lines." (PMID 32151278, 2020). "Six genes involved in Waardenburg syndrome include PAX3 (encoding the paired box 3 transcription factor), MITF (microphthalmia-associated transcription factor), EDN3 (endothelin 3), EDNRB (endothelin receptor type B), SOX10 (encoding the Sry bOX10 transcription factor), and SNAI2 (snail homolog 2)." (PMID 35790984, 2022).
malignant glioma (6 papers, 2010 to 2025). A grade III or grade IV glioma arising from the central nervous system. "It was recently reported that the transcriptional repressors of the snail family, SNAI1 and SNAI2, play a role in the acquisition and increase of invasiveness in malignant gliomas." (PMID 40679044, 2025). "EMT, as a key factor of malignant glioma invasion enhancement, can be characterized by an increase in the expression of biomarkers, such as CDH2, VIM, FN1, SNAI1, SNAI2, ACTA2, and so on." (PMID 34034744, 2021).
head and neck cancer (5 papers, 2017 to 2025). A primary or metastatic malignant neoplasm affecting the head and neck. "Previously, we showed that FOSL1 promoted EMT by activating SNAI2 expression in a superenhancer-dependent manner in head and neck cancer, indicating that FOSL1 is a master regulator of EMT-related transcription factors." (PMID 36185257, 2022). "documented that snail family transcriptional repressor 2 (SNAI2) elevates the expression of FSCN1 at both mRNA and protein levels in head and neck cancer cells by binding the FSCN1 promoter." (PMID 33614909, 2021).
ovarian tumor (5 papers, 2018 to 2025). "In a different ovarian tumor model where SNAI1 and SNAI2 were also found to be mutually exclusive, SNAI1 was found to bind to E-boxes in the promoter region of SNAI2 and recruit HDAC to repress SNAI2 expression." (PMID 37601651, 2023). "We demonstrated here that miR-203 expression inhibits ovarian tumor metastasis by suppressing EMT through targeting BIRC5, in addition through targeting Snai2." (PMID 30241553, 2018).
squamous cell carcinoma (5 papers, 2011 to 2025). A carcinoma arising from squamous epithelial cells. "The role of SNAI2 downstream of Runx2 in BCa is reminiscent of the role of its homologue, SNAI1, in EMT and metastasis of breast, ovarian, colon, lung and squamous cell carcinomas." (PMID 22151997, 2011).
acromegaly (3 papers, 2022 to 2024). Acromegaly is an acquired disorder related to excessive production of growth hormone (GH) and characterized by progressive somatic disfigurement (mainly involving the face and extremities) and systemic manifestations. "Tumor expression of particular genes was found of prognostic/predictive value in acromegaly patients, These genes include basically CDH1 and SSTR2 but also CDKN1B SNAI2, FLNA, ARRB1, SNAI1 RORC ESRP1, and MKI67." (PMID 39497133, 2024).
clear cell renal cell carcinoma (3 papers, 2020 to 2023). "We aimed to determine prognostic value of six key EMT markers (CDH1, CDH2, SNAI1, SNAI2, VIM, TWIST1) in clear cell renal cell carcinoma (ccRCC)." (PMID 31915310, 2020).
colorectal tumors (3 papers, 2018 to 2023). "Although no significant upregulation in SNAI2 mRNA level was observed in this work, SNAI2 protein expression was earlier shown to be upregulated in colorectal tumors." (PMID 29504907, 2018).
leiomyosarcoma (3 papers, 2017 to 2020). An uncommon, aggressive malignant smooth muscle neoplasm, usually occurring in post-menopausal women. "Also, SNAI2 has been described to negatively regulate E-cadherin expression in leiomyosarcoma." (PMID 32532153, 2020). "Silencing the SNAI2 gene could significantly upregulate the expression of CDH1, downregulate the expression of vimentin and CDH2 in leiomyosarcoma cells, and significantly impair the proliferation and invasiveness of cells." (PMID 31749661, 2019). "An integrated proteomics and genomics analyses in soft tissue leiomyosarcomas identified SNAI2/SLUG as a negative regulator of E‐cadherin expression; knockdown of SNAI2 increased E‐cadherin and decreased vimentin expression that was associated with a decrease in proliferation and invasion." (PMID 28556516, 2017). "SNAI2 is not specific for malignant tumors of epithelial origin; it also contributes to the metastasis of tumors of mesenchymal origin, such as osteosarcoma, chondrosarcoma, Ewing sarcoma, leiomyosarcoma, rhabdomyosarcoma, synovial sarcomas, GISTs, fibrosarcoma, and even Kaposi sarcoma." (PMID 31749661, 2019).
mesothelioma (3 papers, 2017 to 2021). A usually malignant and aggressive neoplasm of the mesothelium which is often associated with exposure to asbestos. "Inaddition, SCF/c-Kit/Slug mediates drug resistance in human mesothelioma cells.Knockdown of c-Kit/KIT or SNAI2 increases thesensitivity of mesothelioma cells to the chemotherapeutic agents doxorubicin,paclitaxel, and vincristine." (PMID 33959388, 2021). "In late passage JP4 and JP5 cells there was a concomitant decrease in the expression level of SNAI2, which is consistent with our previous results linking gremlin-1 to a mesenchymal mesothelioma phenotype." (PMID 29228689, 2017). "SNAI2 has been linked to self-renewal capacity of cells as well as to the regulation of EMT processes and is likely an important mediator of gremlin-1 function in mesothelioma." (PMID 29228689, 2017).
oral cancer (3 papers, 2022 to 2025). "All above findings indicated the different roles of TNFRSF25 and TNFRSF12A in p-EMT tumor cells in non- vs. metastasis conditions of oral cancer, and TNFRSF12A is highly associated with tumor cell metastasis transcription factor SNAI2." (PMID 35742914, 2022).
renal carcinoma (3 papers, 2021 to 2023). A carcinoma arising from the epithelium of the renal parenchyma or the renal pelvis. "Among different subgroups in renal cancer scRNAseq data, significant correlations between EMP1/COL3A1 and four EMT genes (VIM, SNAI2, TWIST1, and CTNNB1) were found in c9 fibroblasts." (PMID 38187400, 2023).
Waardenburg syndrome type 2 (3 papers, 2017 to 2023). Waardenburg syndrome type 2 (WS2) is an autosomal dominant subtype of Waardenburg syndrome (WS), characterized by varying degrees of deafness and pigmentation anomalies of eyes, hair and skin, but without dystopia canthorum. "Deficiency in the expression of Snai2 was reported to be associated with Waardenburg syndrome type 2." (PMID 37759439, 2023). "A mutation in SNAI2 has been observed in two patients with Waardenburg syndrome type 2, and MITF has been shown to induce the transcription of SNAI2, the promoter of which has a potential MITF binding site." (PMID 35682684, 2022).
astrocytomas (2 papers, 2010 to 2018). "Elevated expression of SNAI2/Slug mRNA when compared to non-tumor brain (NB) was observed in 2 of 9 (22%) low grade astrocytomas and 6 of 17 (35%) glioblastomas." (PMID 20565806, 2010).
carcinoid tumor (2 papers, 2021 to 2022). A slow growing neuroendocrine tumor, composed of uniform, round, or polygonal cells having monotonous, centrally located nuclei and small nucleoli, infrequent mitoses, and no necrosis. "Two genes (MMP3 and SNAI2) were differently expressed regarding the carcinoid tumor." (PMID 36553576, 2022).
colorectal adenocarcinoma (2 papers, 2020 to 2024). The most common type of colorectal carcinoma. "Low ASPP1 (PP1R13B) expression was significantly correlated with high levels of Snail2 (SNAI2) in the colorectal adenocarcinoma RNASeq data (TCGA dataset, Nature 2012)." (PMID 32269211, 2020).
cutaneous melanoma (2 papers, 2022 to 2023). A primary melanoma arising from atypical melanocytes in the skin. "Normal cutaneous melanocytes have a high expression of SNAI2 and ZEB2 and a low expression of ZEB1 and TWIST1, while malignant cutaneous melanomas have low SNAI2 and ZEB2 and high ZEB1 and TWIST1." (PMID 35682684, 2022).
deafness (2 papers, 2016 to 2020). An inherited or acquired condition characterized by the complete loss of the ability to hear from one or both ears. "Phenotypes caused by the genes endothelin 3 (END3), endothelin receptor B (EDNRB), microphthalmia-associated transcription factor (MITF), paired box 3(PAX3), SRY-box 10 (SOX10), and snail homolog 2 (SNAI2) can result in decreased melanocytes, white coat color, and ultimately deafness." (PMID 27698666, 2016).
ductal carcinoma in situ (2 papers, 2016 to 2017). "ELF5 represses EMT by suppressing SNAI2 expression and down regulating ESR1, and down regulation of ELF5 is detected in all stages of cancer progression including atypical ductal hyperplasia, ductal carcinoma in situ and invasive ductal carcinoma." (PMID 29016359, 2017).
fibrosis (2 papers, 2018 to 2024). the formation of excess fibrous connective tissue in an organ or tissue in a reparative or reactive process. "In these paths, the IPF node is directly connected to either EMT pathway nodes (SNAI2, TWIST1 and ZEB1) or dinoprostone (a pulmonary fibrosis regulator that expresses β-catenin), which is linked to CTNNB1." (PMID 38349059, 2024).
gastric tumor (2 papers, 2016 to 2023). "There was a converse correlation between the levels of miR-506 and SNAI2 expressions in gastric tumor tissues." (PMID 37051101, 2023). "There were also miR-506 and CDH1 up-regulations while SNAI2 down-regulation in gastric tumor cells resulted in reduced cell migration." (PMID 37051101, 2023).
mesenchymal tumors (2 papers, 2013 to 2014). "In support of this view, moderate upregulation of Snai1 or Snai2, as induced in CombitTA-Snai1 and CombitTA-Snai2 transgenic mice, is associated with spontaneous development of epithelial and/or mesenchymal tumors." (PMID 24638100, 2014).
pancreatic ductal adenocarcinoma (2 papers, 2022 to 2023). An infiltrating adenocarcinoma that arises from the epithelial cells of the pancreas. "For example, overexpression of Snai2 in pancreatic ductal adenocarcinoma induces EMT by suppressing epithelial markers and up-regulating mesenchymal markers as a result of which there is increase in migration capacity." (PMID 37414855, 2023).
rectal cancer (2 papers, 2020 to 2024). A primary or metastatic malignant neoplasm that affects the rectum. "Cancer stem cell (CSC) marker ALDH1 and epithelial-mesenchymal transition marker (EMT) markers E cadherin, vimentin, Twist, and SNAI2 expression were evaluated in conjunction with the two optimal reference genes in 10 rectal cancers as part of validation." (PMID 33457124, 2020).
anemia (1 paper, 2023). A reduction in the number of red blood cells, the amount of hemoglobin, and/or the volume of packed red blood cells. "In addition to the macrocytic anemia observed at steady state, stress erythropoiesis was also perturbed in Snai2 KO mice as demonstrated by reduced erythroid recovery following in vivo hematopoietic stress driven by either phenylhydrazine (PHZ)-induced hemolytic anemia or pregnancy-induced anemia." (PMID 37600794, 2023).
Anterior polar cataract (1 paper, 2024). "In addition, the expression level of SNAI family transcriptional repressor 2 (SNAI2) was highly upregulated in lens epithelial cells obtained from patients with anterior polar cataracts, indicating that it may involve in lens development." (PMID 38933921, 2024).
atrial fibrillation (1 paper, 2025). A disorder characterized by an electrocardiographic finding of a supraventricular arrhythmia characterized by the replacement of consistent P waves by rapid oscillations or fibrillatory waves that vary in size, shape and timing and are accompanied by an irregular ventricular response. "These experimental validations confirm the bioinformatics predictions and substantiate our hypothesis that the downregulation of miR-613 observed in atrial fibrillation patients could contribute to disease progression by relieving repression of SNAI2 and CXCR4 expression." (PMID 40549746, 2025). "Our qPCR validation further confirmed that SNAI2 and CXCR4 may be target genes of miRNA-613, and the expression level of these genes was significantly up-regulated in patients with atrial fibrillation, while miRNA-613 was significantly down-regulated in patients suffering from atrial fibrillation." (PMID 40549746, 2025).
B cell deficiency (1 paper, 2013). A broad classification of disorders where circulating numbers of B lymphocytes are decreased or ineffective. "Of these, the Snai2-/- Snai3+/- animals show a greater B cell deficiency than the Snai2+/- Snai3-/- animals." (PMID 23874916, 2013).
chondrosarcoma (1 paper, 2017). A malignant cartilaginous matrix-producing mesenchymal neoplasm arising from the bone and soft tissue. "Furthermore, CCL21/CXCR7 signaling activates the transcription factor SNAI2/Slug via ERK and Phosphatidylinositol-4,5-bisphosphate 3-kinase (PI3K)/AKT signaling in chondrosarcoma, and thus promotes EMT." (PMID 29112161, 2017).